KLF4 (KLF transcription factor 4)
Diseases named in the same sentence as KLF4 in open-access papers (continued):
Sharing a sentence is not in itself a finding about the gene and the disease.
colorectal cancer (100 papers, 2011 to 2026). A primary or metastatic malignant neoplasm that affects the colon or rectum. "In a previous study examining colorectal cancer, downregulated KLF4 expression was associated with a poor prognosis." (PMID 40299916, 2025). "Oppositely, KLF4 loss in early colorectal cancers due to targeted proteasome-dependent degradation designates its function as a tumor-suppressor through inhibiting tumorigenesis via regulation of cell-cycle arrest." (PMID 37835497, 2023). "KLF4 as a tumor suppressor inhibits colorectal cancer cell growth and is associated with poor overall survival." (PMID 35194111, 2022). "KLF4 is often deleted in gastrointestinal tumors, which can cause tumor growth of gastric cancer and colorectal cancer." (PMID 34367275, 2021). "Typically using the Villin-Cre driver to effect intestinal deletion, studies showed that KLF4 loss was protective against development and progression of colitis-associated colorectal cancer (CAC) by guarding against genetic instability." (PMID 33266506, 2020). "Krüppel‐like factor 4 (KLF4) was closely associated with epithelial‐mesenchymal transition and stemness in colorectal cancer stem cells (CSCs)‐enriched spheroid cells." (PMID 31830379, 2020). "The intestinal epithelium-specific deletion of Klf4 in mice increases genetic instability and accelerated progression of colitis-associated colorectal cancer (CAC)." (PMID 33266506, 2020). "The KLF4 activity score is associated with tissue remodelling, myeloid cell infiltration and poor prognosis in colorectal cancer." (PMID 30287917, 2018). "A similar phenomenon was reported in colorectal cancer cell lines, where KLF4 mutations resulted in reduced p21CIP promoter activity." (PMID 25037230, 2014). "Exposure of colorectal cancer cell lines to hypoxia has been shown to result in enhanced expression of miR-103/107 that targeted the metastasis suppressors KLF-4 and death-associated protein kinase (DAPK), conferring an invasive phenotype on them." (PMID 23185562, 2012). "Prior studies in human colon cancer cell lines and primary colorectal cancers implicated hypermethylation of the KLF4 gene promoter, loss of heterozygosity, or mutation of the open reading frame." (PMID 23006636, 2012). "Many colorectal cancers occur under the condition that the presence of mutation in the Wnt pathway and down-regulation of Klf4." (PMID 21687630, 2011). "KLF4 encodes a tumor suppressor and its methylation can lead to silencing of the gene, which has been reported in variety of cancers such as pancreatic cancer, leukemia, colorectal cancer, and medulloblastoma." (PMID 34854470, 2022). "Notably, epithelium-specific ablation of Klf4 results in enhanced pathology in the colitis-associated colorectal cancer model." (PMID 34911745, 2021). "Next we investigated whether the KLF4 activity score is associated with immune cell infiltration in colorectal cancer samples." (PMID 30287917, 2018). "In conclusion, the present meta-analysis according to published articles demonstrated that loss of KLF4 expression was associated with poorer survival in most kinds of digestive system cancer patients, such as gastric, hepatic, pancreatic, and colorectal cancers." (PMID 29062163, 2017). "Finally, hypoxia-induced miR-103/107 targets the tumor suppressors death-associated protein kinase (DAPK) and Kruppel-like factor 4 (KLF4) to promote metastasis of colorectal cancer." (PMID 23241400, 2012). "Although substantial research supports the tumor-suppressive role of KLF4, its function in colorectal cancer (CRC) remains controversial." (PMID 39995670, 2025). "KLF4 expression promotes radioresistance of colorectal cancer (CRC) cell lines, and its tumor-promoting role seems to be also confirmed in patient-derived xenograft (PDX) models of CRC." (PMID 40863723, 2025). "In colorectal cancer, sulforaphane induces KLF4 and enhances KLF4-p21 signaling, contributing to the inhibition of cancer cell growth and promoting differentiation." (PMID 39995670, 2025).
colorectal cancer (continued). "KLF4 is of interest due to its tumor suppressor functionality in various types of cancer cells, most notably, in colorectal cancer (CRC) cell lines." (PMID 40699616, 2025). "There were multiple microRNAs downregulating KLF4, including microRNA-92a and microRNA-10b, promoting colorectal cancer growth, migration, proliferation, and metastasis." (PMID 37031197, 2023). "In a clinical trial, metformin had a positive effect on colorectal cancer and endometrial cancer by increasing KLF4 expression." (PMID 37031197, 2023). "It has shown that the increased KLF4 marker as a tumour suppressor can successfully suppress the proliferation or migration of colorectal cancer cells, which was also in agreement with the results of the present study." (PMID 37201032, 2023). "For example, miR-543 was proved to accelerate the proliferation and metastasis of colorectal cancer by targeting KLF4." (PMID 37273453, 2023). "MiRNA29a promotes colorectal cancer cell metastasis via the down-regulation of KLF4 and e-cadherin, and up-regulation of MMP2." (PMID 37670299, 2023). "KLF4 reportedly acts as a tumor suppressor in gastric cancer 55, colorectal cancer 56, bladder cancer 57 and prostate cancer 58, where a significant decrease or loss in KLF4 expression is frequently observed." (PMID 35982899, 2022). "KLF4 and EGR1 together have been implicated in inducing ATF3 transcription and subsequent apoptosis in resveratrol-treated human colorectal cancer cells." (PMID 35746681, 2022). "KLF4 is a zinc finger transcription factor that functions as a tumour suppressor (in lung, gastric, and colorectal cancers) or a tumour promoter (in breast ductal carcinoma and oral/skin squamous cell carcinoma), depending on cancer type." (PMID 35359381, 2022). "In intestinal tumors and colorectal cancer cells, the Notch signaling can inhibit the expression of KLF4 and reduce proliferation and tumor formation." (PMID 34367275, 2021). "A previous study has shown that KLF4 acts as a tumor suppressor in colorectal cancer and KLF4 plays an important role in γ-ray-induced DNA damage repair." (PMID 34367275, 2021). "The aim of this study was evaluation the effect of orlistat on the expression of OCT4, Nanog, SOX2, and KLF4 genes in the colorectal cancer SW40 cell line." (PMID 34452543, 2021). "B-cell-specific Moloney murine leukemia virus insertion site 1 (BMI1) deficiency sensitizes cells to radiation treatment by modulating the expression of KLF4 and leads to enhanced radiosensitivity in microsatellite stable colorectal cancers." (PMID 33266506, 2020). "The analysis of cell proliferation and tissue remodeling from the cohort of colorectal cancer patients have also predicted KLF4 to be a driver of tissue remodeling in CRC via myeloid cell infiltration." (PMID 33266506, 2020). "KLF4 was reported to be a tumor suppressor in colorectal cancer, possibly through elevating the Von Hippel-Lindau gene product, pVHL." (PMID 32756012, 2020). "For example, miR-25-3p induces colorectal cancer angiogenesis by inhibiting the expression of KLF4, thereby downregulating the expression of VEGFR2 in HUVECs." (PMID 32958011, 2020). "The research of Zhao WD identified the functional role of KLF4 suppressing colorectal cancer progression." (PMID 32756012, 2020). "KLF4 inhibits the G1/S transition of the cell cycle and has been identified as a potential tumor suppressor gene in colorectal cancer." (PMID 33396408, 2020). "Transcriptional repressor Kruppel-like factor (KLF4) inhibits the abnormally differentiated cells in colorectal cancer and HES-1, a downstream molecule of Notch-1, can inhibit the expression of KLF4." (PMID 31198409, 2019). "Among them, we follow up on KLF4 activity that we predict to be a driver of tissue remodelling in colorectal cancer." (PMID 30287917, 2018).
colorectal cancer (continued). "Among the candidates, we identified KLF4 as a TF whose activity score is significantly correlated with the tissue remodelling enrichment score, which is indicative of poor prognosis in colorectal cancer." (PMID 30287917, 2018). "A previous work indicated that Notch signaling supresses KLF4 expression in intestinal tumors and colorectal cancer cells." (PMID 28086833, 2017). "The loss of tumor suppressor APC resulted in the activation of MSI-2 in colorectal cancer, and reduced expression KLF4 (a transcriptional repressor of MSI-2) led to MSI-2 overexpression in pancreatic cancer." (PMID 29073938, 2017). "A study of colorectal cancer cells demonstrated that PPARγ regulates KLF4 transcription by directly binding to the KLF4 promoter." (PMID 27483249, 2016). "In colorectal cancer, introduction of a set of defined factors (Oct3/4, Sox2 and Klf4) showed an enhancement in CSC properties such as sphere formation capability, expression of CSC marker genes, chemo-drug resistance, and tumorigenicity." (PMID 26683522, 2016). "MiR-29a promoted colorectal cancer metastasis by regulating matrix metalloproteinase 2 and E-cadherin via KLF4." (PMID 27302923, 2016). "KLF4 has been reported to act as a tumor suppressor in some cancer types, such as lung carcinoma, gastric cancer and colorectal cancer." (PMID 27835585, 2016). "The signature of a high miR-103/107, low DAPK and low KLF4 expression profile correlates with the extent of lymph node and distant metastasis in patients with colorectal cancer." (PMID 26146543, 2015). "Specifically, loss of hsa-miR-10a that targets KLF4, as seen in STIM1 overexpression patients, led to upregulation of LPO and initiation of colorectal carcinomas." (PMID 26543234, 2015). "Several studies have shown that KLF4 mRNA and protein expression is reduced in human colorectal cancer." (PMID 25060774, 2014). "The purpose of this study was to determine the significance of KLF4 in both tumors and normal tissues of patients with colorectal cancer (CRC)." (PMID 25060774, 2014). "The antagonistic effect of KLF4 on tumorigenicity and disease progression was further demonstrated in colorectal carcinoma (CRC)." (PMID 24429391, 2014). "Evidence also suggests that KLF4 is a tumor suppressor in certain cancers including colorectal cancer." (PMID 23919723, 2013). "In most colorectal cancers Notch signaling was found to be activated, whereas Hath1 and KLF4 were decreased." (PMID 23418447, 2013). "Hypermethylation is observed in the promoter region of KLF4 in several cancers, including colorectal cancer, hepatic cancer, and lung cancer." (PMID 23861801, 2013). "In summary, our lab previously identified KLF4 as a potential tumor suppressor in colorectal cancer in which KLF4 level is reduced in tumor tissues relative to normal tissues." (PMID 23919723, 2013). "Loss of the KLF4 region on chromosome 9q is reported in 25% to 50% of sporadic colorectal cancers, and a significant decrease in KLF4 expression is observed in adenomas and adenocarcinomas of the large and small intestine." (PMID 23006636, 2012). "Reduced klf4 expression was detected in a number of colorectal cancer cell lines which was attributed to either hemizygous deletion of klf4 gene, hypermethylation of 5′untranslated region or point mutation in the open-reading frame." (PMID 21687630, 2011). "For instance, in colorectal cancer (CRC) circRNAs affect the axis miR-29a-3p-KLF4." (PMID 40863723, 2025). "Furthermore, KLF4 is downregulated in colorectal cancer, promoting uncontrolled cell proliferation and metastasis, which are hallmarks of cancerous cell types." (PMID 40699616, 2025). "KLF4 inhibited colorectal cancer cell proliferation through upregulating p21 and NDRG2 (a molecule downstream of Myc), and downregulating cyclinD1 (the key molecule of cell cycle G1/S extension), GINS complex subunit 4 (GINS4), and IFITM3 (a tumor metastasis-associated molecule)." (PMID 37031197, 2023).
colorectal cancer (continued). "These evidences elucidate an antitumor role of KLF4 as a tumor suppressor in colorectal cancer." (PMID 37031197, 2023). "Rescue experiments revealed that miR-7-5p/KLF4 axis could induce radiosensitivity by regulating CSCs in colorectal cancer cells." (PMID 36732504, 2023). "KLF4 was downregulated in human colorectal cancer tissues as compared with normal mucosa." (PMID 37031197, 2023). "The antitumor role of KLF4 in colorectal cancer is evidently clear." (PMID 37031197, 2023). "KLF4 acted as a tumor suppressor to inhibit the colorectal cancer growth in mice." (PMID 37031197, 2023). "We then sought to examine conservation of MEX3A / KLF4 relationship in human colorectal cancer." (PMID 36276637, 2022). "Among the top genes emerging from limma analysis, we found four genes particularly related to cancer stemness and CRC CSCs: besides the pluripotency factor KLF4, we found three genes were specifically related to colorectal cancer stemness and self renewal, i.e., AXIN2, LGR5 and BMI1." (PMID 36077264, 2022). "KLF4 stimulates stemness and mesenchymal properties of colorectal cancer stem cells by the activation of the TGF-β1 pathway, which might be involved in the KLF4-associated spheroid formation of the gastric cancer cells." (PMID 36661504, 2022). "KLF4 is downregulated in colorectal carcinoma, and gastric epithelium, suggesting that it might be a tumor suppressor." (PMID 36101460, 2022). "However, in some other tumours (such as oesophageal cancer, gastric cancer, medulloblastoma, bladder cancer, pancreatic cancer, colorectal cancer and pancreatic duct cancer), KLF4 plays a role in inhibiting the growth and proliferation of tumour cells." (PMID 33342082, 2021). "However, KLF4 is downregulated in many patients with epithelial cancer, including esophageal cancer, gastric cancer, colorectal cancer, and bladder cancer, leading to cell proliferation." (PMID 34367275, 2021). "KLF4 has been widely reported as an oncogene in multiple cancer types, including lung cancer, ovarian cancer, esophageal squamous cell cancer, gastric cancer, colorectal cancer, and leukemia." (PMID 34722520, 2021). "By targeting KLF4, miR-543 facilitates colorectal cancer proliferation and metastasis." (PMID 33266506, 2020). "For example, KLF4, which is zinc-finger transcription factor, is a tumor suppressor in colorectal cancer and may act as oncogene in oral squamous cell carcinoma." (PMID 33066530, 2020). "In addition, miR-375 exerts an inhibitory effect on the proliferation of colorectal cancer by targeting the 3′UTR of KLF4." (PMID 32211396, 2020). "The broadly described role of KLF4 in colorectal cancer (CRC) remains controversial." (PMID 33266506, 2020). "In conclusion, this study indicated that miR-543 facilitates colorectal cancer proliferation and metastasis by targeting KLF4, and miR-543 may serve as a promising target for the treatment of CRC patients." (PMID 28938633, 2017). "MiR-103 and miR-107 promote metastasis of colorectal cancer by KLF4 and DAPK." (PMID 27302923, 2016). "miR-10b, miR-206 and miR-103/107 have been characterized as oncomiRs as their overexpression in esophageal and colorectal cancer correlates with enhanced proliferative and/or metastatic phenotypes that result from the downregulation of the tumor suppressor KLF4." (PMID 25181544, 2014). "In colorectal cancer tissue hsa-miR-103 might promote metastasis by targeting the known metastasis suppressors death-associated protein kinase (DAPK) and Krüppel-like factor 4 (KLF4)." (PMID 25175044, 2014). "However, in colorectal cancer the KLF4:β-catenin interaction is lost due to KLF4 downregulation causing de-repression of the Wnt signaling and uncontrolled cell proliferation." (PMID 25181544, 2014). "KLF4 is down-regulated in colorectal cancers and has been identified as a tumor suppressor." (PMID 22384261, 2012).
colorectal cancer (continued). "KLF4 is an epithelial transcription factor that might be played the role of a tumour suppressor or an oncogene depending on the context of tumours and is downregulated in many colorectal cancers." (PMID 37201032, 2023). "Additionally, it was reported that KLF4, a target of miR-7, acts as an oncogene in colorectal cancer, so the inhibition of KLF4 expression by miR-7 is a mechanism and a potential molecular target for the treatment of colorectal cancer." (PMID 36012357, 2022). "Moreover, the studies have also shown that CXCL/CXCR and PI3K/AKT/STAT3 signaling pathways participate in the regulation of EMT- and cancer stem cell- associated events, and up-regulate the expression of Snail, Twist, ZEB1, Oct4, Sox2, c-Myc, Nanog and KLF4 in colorectal cancers." (PMID 28350360, 2017). "Further, using the DNA damage drug etoposide, a topoisomerase II poison, we further investigated the connection of Klf4 to the DNA damage response in RKO, human colorectal cancer cell lines." (PMID 40699616, 2025). "In this study, cultured MEFs wild type (+/+) and null (−/−) for Klf4 and human carcinoma colorectal (RKO) cells were studied as a model for human colorectal cancer." (PMID 40699616, 2025). "In colorectal cancer, β‐catenin interacts with lymphoid enhancing factor (LEF‐1) and Krüppel‐like factor 4 (KLF4) to increase or decrease tumor cell proliferation, respectively." (PMID 38826147, 2024). "The current review expands on the role of KLF4 and KLF5 in animal models of colorectal cancer, providing recent discoveries in their involvement in regulating the development, progression, and metastasis of CRC." (PMID 37173904, 2023). "For instance, KLF4 exerted the oncogenic functions through transcriptional activation of TGF‐β1 to maintain stemness and mesenchymal capacities of colorectal cancer stem cells." (PMID 37179359, 2023). "Colorectal cancer cell derived exosomes miR-25-3p targeted KLF2 and KLF4 to regulate the expression of VEGFR2, ZO-1, occludin and Claudin5, increase vascular permeability and promote angiogenesis." (PMID 35173549, 2022). "Our data enhanced the relationship between Klf4 and CA1, indicating that the two are most likely coexpressed in colorectal cancer cells." (PMID 32908896, 2020). "KLF4 regulates stemness and mesenchymal properties of CRC stem cells through the TGF-β1/Smad/snail pathway in Lgr5+CD44+EpCAM+ colorectal cancer stem cells (CSCs), which are responsible for initiating and sustaining tumor development and progression." (PMID 33266506, 2020). "Immunofluorescence staining for KLF4 and EMT markers was performed on archived patient samples after colorectal cancer resection and on colonic tissues of mice with colitis-associated cancer." (PMID 32566755, 2019). "The zinc-finger transcription factors KLF4 and Slug are indispensable for sustaining the CSC properties in multiple cancers, including breast, lung, and colorectal cancers." (PMID 31526394, 2019). "The overexpression of miR-103 and miR-107 in a mouse model of colorectal cancer was shown to promote local invasion and liver metastasis by targeting DAPK and KLF4." (PMID 26146543, 2015). "Recent reports showed miR-103 was expressed in colorectal cancer as an oncogenic miRNA by targeting DAPK, KLF4 and PER3." (PMID 26511107, 2015). "miR-103 and miR-107 promote colorectal cancer metastasis by targeting DAPK and Krüppel-like factor 4 (KLF4)." (PMID 25893379, 2015). "The role of FABP2 in colorectal cancer stem cells and differentiation: In colorectal cancer stem cell research, FABP2 has been found to co-regulate with intestinal epithelial differentiation markers (such as KLF4, CA1)." (PMID 40717587, 2025). "KLF4-positive colorectal cancer patients with lymph node metastasis had a better overall survival than KLF4-negative patients with lymph node metastasis." (PMID 40863723, 2025). "This review will focus on KLF4 and KLF5’s role in colorectal cancer (CRC) tumorigenesis." (PMID 37173904, 2023).